CTLA4 (cytotoxic T-lymphocyte associated protein 4)
Diseases named in the same sentence as CTLA4 in open-access papers (continued):
Sharing a sentence is not in itself a finding about the gene and the disease.
tumor (continued). "In addition, it has recently been shown that local radiotherapy and CTLA-4 blockade significantly reduce the motility of tumor infiltrating lymphocytes at tumor sites, allowing them to engage in stable interactions with tumor targets." (PMID 24434638, 2014). "Among checkpoint molecules, CTLA-4 blockade was the first shown to enhance anti-tumor responses." (PMID 24339825, 2013). "It has previously been found that combination therapy with anti-CTLA-4 and anti-4-1BB antibodies may enhance tumor immunity." (PMID 23785471, 2013). "No statistical significances were found (P > 0.05) regarding the association between the studied CTLA-4 polymorphisms in PBMCs and patients' characteristics (age, gender, smoking history), NSCLC subtypes (SCC, AC, and LCC) and tumor staging (TNM and AJCC systems)." (PMID 23936819, 2013). "Taken together, these data suggest that CTLA-4 blockade in combination with DC vaccination could break tolerance to tumor-specific antigens, resulting in tumor clearance, and long-term host immunity after tumor re-challenge." (PMID 24348481, 2013). "In data from experiments in multiple tumor models involving treatment with CTLA-4 blockade and/or chemotherapeutic agents, synergy was observed in settings where blockade with anti-mCTLA-4 mAb alone was ineffective or in models where the chemotherapeutic agent alone did not induce tumor regression." (PMID 23873089, 2013). "In addition, tumor-infiltrating Tim-3+Foxp3+ CD4 T cells expressed higher levels of CTLA-4, GITR and PD-1 compared with Tim-3−Foxp3+ CD4 T cells." (PMID 23526963, 2013). "Though in some cases tumor regression was obtained by adoptive transfer of TIL or tumor specific antigen vaccines, tumor responses have also been achieved using immunostimulatory cytokines and antibodies that block immunosuppressive signals, e.g. CTLA4." (PMID 23514280, 2013). "This combination may also overcome resistance to CTLA-4 blockade mediated by tumor PD-L1 expression or resistance to PD-1 blockade mediated by T-cell downregulation through the coexpression of CTLA-4." (PMID 24403232, 2013). "However, the CTLA-4+ Tregs were still abnormally elevated, even in those whose tumours showed a cPR, when compared with HFDs (p = 0.024)." (PMID 23320561, 2013). "However, following completion of treatment, the reduced AbNs of CTLA-4+ Tregs in patients whose tumours showed a cPR were still 3 fold elevated, when compared with HFDs (p = 0.005)." (PMID 23320561, 2013). "Indeed, in vivo administration of blocking antibodies against CTLA-4 resulted into effective anti-tumor immunity and tumor rejection." (PMID 23450201, 2013). "CTLA-4 has also been shown to have an impact on T cell responses in animal tumor models and humans." (PMID 23289632, 2013). "Although all naïve mice developed tumors that grew progressively, each of the mice treated with etoposide in combination with anti-mCTLA-4 mAb (n = 4) rejected tumor rechallenge, leading the authors to interpret that combination of CTLA-4 blockade plus etoposide generated a memory immune response." (PMID 23873089, 2013). "The tumor microenvironment in CLL suppresses the expression of CTLA4." (PMID 23936412, 2013). "To assess whether anti-CTLA-4 could mediate an additive or synergistic anti-tumor effect, we performed longitudinal treatment studies using ProHA × TRAMP mice." (PMID 23557194, 2013). "While their differential expression is yet to be assigned to either iTreg or nTregs cells, CCR4, PD-1, and CTLA-4, which have been shown to be highly expressed on tumor-Treg cells offer potential targets for treatment of cancers enriched in Treg cells with such phenotype." (PMID 23874336, 2013). "In this way, CTLA-4 molecule as a negative regulator of tumor cell proliferation might influence the clinical outcome of patients with cancer." (PMID 23936819, 2013).
tumor (continued). "In particular, it could be of use to study pseudo-progression noted with some forms of immunotherapy (such as the anti-CTLA4 antibody ipilimumab), where some patients may have an initial period of apparent tumor progression before having a response." (PMID 24829750, 2013). "In addition, many members of the B7-homolog (B7-H) family, such as PD-1 and CTLA-4, are expressed on tumour cells in various cancers, where they can be exploited by the cancerous cells to escape from immune destruction and impede B7 ongoing immune processes." (PMID 23829304, 2013). "However, even where the tumour showed a cPR there was still a significant elevation of CTLA-4+ AbNs, when compared with HFDs (p = 0.004)." (PMID 23320561, 2013). "Early preclinical studies demonstrated that blockade of CTLA-4 could mitigate inhibition of anti-tumor immune responses." (PMID 24829749, 2013). "Prior studies have demonstrated that while combined therapy with GVAX and CTLA-4 blockade may result in increased absolute numbers of Tregs, increases in the Teff:Treg ratio are characteristic of an effective anti-tumor response." (PMID 23557194, 2013). "Patients showed strong expression of CTLA-4 in tumor cells of all specimens." (PMID 23861693, 2013). "However, when anti-CTLA-4 and gemcitabine were combined, a clear additive effect of both treatments with a significant delay of tumor outgrowth was observed." (PMID 23626745, 2013). "CD4+ T cell infiltration in the tumor was enhanced by the combination treatment, and a gemcitabine-associated decrease in proliferating tumor-infiltrating CD8+ T cells was partly rescued by CTLA-4 blockade." (PMID 23626745, 2013). "We tested whether combination treatment with anti-CTLA-4 and gemcitabine resulted in anti-tumor immunological memory." (PMID 23626745, 2013). "Therefore, the presence of CTLA-4 on tumor Treg would indicate active suppression of the anti-tumor immune response." (PMID 22319577, 2012). "However, combinatory treatment with CTLA-4 blocking agents and fractionated RT resulted in a significant growth retardation of the tumor outside the radiation field." (PMID 23087898, 2012). "However, the combination of 4-1BBL-expressing vaccine and CTLA-4 blockade induced more obvious effectiveness on RM-1 tumor growth than either treatment alone." (PMID 22312406, 2012). "We found that the combination of both a vaccine consisting of 4-1BBL-expressing RM-1 cells and CTLA-4 blockade resulted in regression of RM-1 tumors and a significant increase in survival of the tumour cell recipients, compared to that of either treatment alone." (PMID 22312406, 2012). "Moreover, preventing CD80 expression on MDSC or the use of anti-CTLA-4 antibodies delay tumor growth, suggesting that CTLA-4/CD80 interaction between MDSC and Treg is necessary for their activity or their development." (PMID 22822406, 2012). "Crosslinking of T cell activating CD28 may be less important than blocking the inhibitory CTLA-4, since activated T cells recognizing tumor antigens require less costimulation." (PMID 24955288, 2012). "We also used the two tumor models to test an immuno-gene therapy approach for anti-CTLA4." (PMID 21779410, 2011). "Additionally, we found less cytokines that are involved in the activation of anti-tumor immune responses and attraction of T-cells in anti-CTLA4 expressing tumors." (PMID 21779410, 2011). "Expression of anti-CTLA4 antibodies inside the tumor has advantages over systemic administration." (PMID 21779410, 2011). "In this study, we used two tumor models that assess anti-CTLA4 antibody therapy." (PMID 21779410, 2011). "In general, it appears that strategies that kill tumor cells or prime T cells may be enhanced by combination with CTLA-4 blockade." (PMID 21281484, 2011). "The blockade of the CTLA-4 pathway results in a rejection of tumor, indicating that a lower CTLA-4 expression may be important for antitumor response." (PMID 21992110, 2011).
tumor (continued). "A portion of the anti-tumor effect of CTLA-4 blockade derives from inhibition of Tregs; however, the effects of α4-1BB on Treg proliferation and suppression remain unclear." (PMID 21559358, 2011). "The data presented here suggests that combining antibody blockade of PD-1 or both CTLA-4 and PD-1 with activation of 4-1BB may provide substantial benefit to auto-tumor immune responses." (PMID 21559358, 2011). "These anti-CTLA-4-treated mice were subsequently completely immune to the tumor upon re-challenge." (PMID 21281484, 2011). "Other tumor-associated antigens, such as the adhesion molecule EpCAM, the epithelial mucins CA125 and MUC1, and the Folate Receptor as well as molecules expressed by immune cells such as CD3 and CTLA-4 are under evaluation." (PMID 22235224, 2011). "Interestingly, Dox induced anti-CTLA4 expression appeared to increase the percentage of NK cells in the tumor and spleen." (PMID 21779410, 2011). "However, when we employed the HSC-based approach for in vivo expression of anti-CTLA4, we found a marked stimulation of TC-1 tumor growth upon Dox induction of anti-CTLA4 expression." (PMID 21779410, 2011). "Interestingly, α4-1BB appeared to decrease the proliferation of tumor-infiltrating Tregs, but much of this effect was lost in combination with CTLA-4 blockade." (PMID 21559358, 2011). "To understand the apparent synergy between CTLA-4 blockade and 4-1BB activation in the context of our Flt3-ligand base vaccine, we sought to dissect the effects of each therapy on T-cell infiltration of tumor in this background." (PMID 21559358, 2011). "In a therapeutic approach, anti-CTLA-4 was administered to patients with metastatic melanoma and resulted in tumor regression in 21% of the patients, but 43% developed grade III and IV autoimmune manifestations in the form of dermatitis, enterocolitis, hepatitis, hypophysitis and others." (PMID 24281039, 2010). "Combined administration of anti-CTLA-4 and GM-CSF seems to enhance the anti-tumor effect." (PMID 24281039, 2010). "A similar skewed ratio has recently been reported with an agonist anti-OX40 mAb, as well as antagonist anti-CTLA4 mAb, suggesting that an altered intra-tumor Teff:Treg ratio may be predictive of anti-tumor activity of these immune-modulating approaches." (PMID 20454651, 2010). "Also, the number of cells staining positive for FoxP3 by immunohistochemistry increases in tumor biopsies of regressing lesions after CTLA4 blockade." (PMID 19457253, 2009). "Thus, blockade of CTLA-4 inhibitory signals during T cell-APC interactions can result in enhanced tumor immunity." (PMID 19175928, 2009). "Further effective tumor immunity was provoked in Treg-restricted-CTLA-4-/- mice." (PMID 19175928, 2009). "Elimination or inhibition of Treg activity by low-dose cyclophosphamide or antibodies against CD25 or CTLA-4 may modify tumor immunosuppressive microenvironment, thereby increasing the efficacy of immunotherapy." (PMID 19272130, 2009). "It remains to be investigated, however, whether CTLA4 depletion might also interfere with the clonal expansion of tumor-antigen specific T lymphocytes." (PMID 18431473, 2008). "Since our tumour challenge experiments with addition of CTLA-4 blockade didn't correlate well with CTL levels in an experimental LCMV tumour model, it is unknown if this DC depletion will influence the outcome of a tumour vaccine." (PMID 17662155, 2007). "Finally, we show that in situ tumour ablation can be efficiently combined with immune modulation by anti-CTLA-4 antibodies or regulatory T-cell depletion." (PMID 16953240, 2006). "In addition to these stimulatory pathways, also blockade of inhibitory receptors, for example, CTLA-4, has been applied successfully to induce tumour rejection." (PMID 16953240, 2006).
tumor (continued). "We found that targeting CD47, a macrophage checkpoint molecule, leads to anti-tumor activity via the induction of tumor cell phagocytosis and non-apoptotic cell death, providing an alternative therapeutic approach to adaptive immune checkpoint blockade strategies such as PD-1 and CTLA-4 inhibitors." (PMID 41484790, 2026). "Studies have also shown that PTEN deficiency promotes resistance to anti‐PD1 and anti‐CTLA4 therapies and that inhibition of the PIK3/AKT pathway in PTEN‐deficient tumor cells could overcome the immunosuppressive tumor phenotype and the resistance to immune checkpoint inhibitors." (PMID 41578916, 2026). "In LIHC, DCAF7 correlated strongly with PD‐1/PD‐L1 and CTLA‐4 expression, implying that tumours with elevated DCAF7 might preferentially exploit checkpoint pathways for immune evasion and could therefore benefit from dual targeting of DCAF7‐driven signalling and checkpoint blockade." (PMID 41472554, 2026). "Furthermore, the combination of curcumin with PD-L1 blockers or CTLA-4 blockers may have a synergistic effect compared to monotherapy, further inhibiting tumor growth, promoting T-cell activation, inhibiting Treg infiltration, and dramatically improving TME." (PMID 41522360, 2026). "Studies have shown that the anti-tumor effect of CTLA-4 blockade therapy depends on specific Bacteroides species, especially Bacteroides thetaiotaomicron and B. fragilis, which can enhance tumor immune responses by promoting T cell activation and tumor-infiltrating lymphocyte function." (PMID 39921821, 2025). "Furthermore, the heightened functionality of cytotoxic T cells and NK cells in N2G mice facilitates reliable evaluation of immune checkpoint inhibitors (e.g., anti-PD-1, anti-CTLA-4), particularly in settings requiring robust tumor infiltration and T cell activation." (PMID 40643795, 2025). "However, simultaneous treatment of mice with PD-L1 and CTLA-4 antibodies allows for restored expression of CD80 on tumor-associated DCs, leading to increased CD28 costimulation, downstream T cell responses, and reduced overall tumor burden." (PMID 39879305, 2025). "Notably, JunB is critical for the suppressive functions of Treg cells and regulates key effector molecules such as CTLA-4, which may result in unfavourable inhibition of the anti-tumour response." (PMID 39859271, 2025). "Additionally, correlation analysis of immune phenotype scores indicated that in COAD, KIRC, LIHC, LUAD, STAD, THCA, and UCEC, tumor patients with low SF3B6 expression were anticipated to experience improved immunotherapy responses following treatment with CTLA-4 or PD-1 blockade." (PMID 40356980, 2025). "While current immunotherapies targeting PD-1/PD-L1 and CTLA-4 have shown remarkable success in certain cancers, their efficacy remains limited by immunosuppressive tumor microenvironments and the “cold tumor” phenotype characterized by poor T cell infiltration." (PMID 41154604, 2025). "It is worth noting that single cell TCR sequencing confirmed that CTLA-4 inhibitor combined with PD-1 blocker synergistically enhanced the temporal and spatial dynamics of T cell clones, significantly improving the breadth and persistence of anti-tumor immunity." (PMID 41425703, 2025). "Future optimization efforts may include incorporating PD-1 or CTLA-4 blockade as combinational therapies, exploring additional preclinical models such as orthotopic tumor models, and refining degrader design to enhance in vivo performance and translational potential." (PMID 41038820, 2025). "Resistance arises from both tumor-intrinsic factors and adaptive immune evasion, prompting investigation into alternative inhibitory pathways that may undermine or compensate for PD-1/CTLA-4 targeting." (PMID 41013723, 2025).
tumor (continued). "On the other hand, F-box proteins directly regulate tumor immune microenvironments by targeting immune-related molecules for degradation, thereby modulating T-cell activation, macrophage polarization, and immune checkpoint functionality (specifically PD-1/PD-L1 axis and CTLA-4 signaling)." (PMID 40534867, 2025). "Finally, the lower Immune Profile Score (IPS) observed in the high EPHX4 expression group indicates that EPHX4 could impact tumor immune evasion mechanisms, potentially reducing responses to anti-CTLA-4 and anti-PD-1 therapies." (PMID 40507905, 2025). "By conjugating PD-L1 and CTLA-4 inhibitors, as well as cytokines like IL-2, with a collagen-binding motif derived from the von Willebrand factor A3 domain, these agents can be selectively delivered to tumor sites, improving treatment specificity and efficacy 899,900." (PMID 41281748, 2025). "However, the result of the chemo > STING/α-PD-1 + α-CTLA-4 group may be influenced by one mouse that had an extremely low number of DCs in the tumor-draining lymph nodes." (PMID 39871312, 2025). "Enhancing PD-1 or CTLA-4 activity may weaken tumor immunosurveillance, particularly in patients with latent or undiagnosed malignancies, as forced PD-1 expression has been shown to promote tumor cell proliferation through SHP2–Ras–MAPK signaling." (PMID 41463504, 2025). "Given the variability of the responses to anti–CTLA-4 antibody therapy, we aimed to analyze the biological responses associated with “responders” and “nonresponders” (responders: tumor growth inhibition rate above median, nonresponders: tumor growth inhibition rate below median, median = 72.3%)." (PMID 39881590, 2025). "Given the role Tregs play in inhibiting effector T cells and suppressing anti-tumor immunity, multiple agents with anti-Treg activity have been evaluated across different tumor types, including cytotoxic agents like cyclophosphamide and immune interventions such as anti-CTLA-4 antibodies." (PMID 40006664, 2025). "Consequently, genetic polymorphisms may disrupt the functionality of molecules critical for the efficacy of the anti-tumor response, such as CTLA-4." (PMID 41141615, 2025). "Additionally, the strong presence of PD-1 and its ligands on tumor cells and TILs indicated that blocking this route could result in less severe immunological toxicity toward healthy cells than CTLA-4 blockage." (PMID 39994019, 2025). "Additionally, in I3 subtype, proliferating Tregs and myeloid cells also express various immune checkpoints such as PD-1 and CTLA-4, which interact with receptors ex­pressed on tumor-infiltrating immune cells, further promoting the formation of an immunosuppressive environment." (PMID 41236411, 2025). "By blocking intrinsic downregulators of immunity, such as cytotoxic T-lymphocyte antigen 4 (CTLA-4), programmed death 1 (PD-1), and programmed death-ligand 1 (PD-L1), they disrupt the immune escape mechanism of tumor cells and significantly enhance anti-tumor immune responses." (PMID 41226056, 2025). "Considering previous reports showing that anti-CTLA-4 mainly targets lymph node T cells and increases tumor infiltration by new effector T cells, intratumoral T cell dysfunction reflected by sCD27 could be less associated with resistance to the anti-CTLA-4 + anti-PD-1 combination." (PMID 40148586, 2025). "Tumor cells, on the other hand, induce the proliferation and infiltration of immunosuppressive cells (e.g., Tregs, MDSCs, M2-type macrophages), highly express immune checkpoint molecules such as PD-L1 and CTLA-4, and ultimately form an immunosuppressive microenvironment." (PMID 40356913, 2025). "Since CTLA4 inhibitors may allow for the formation of de novo immune responses, one possible explanation for this outcome is that higher doses may create new anti-tumor responses." (PMID 40136348, 2025).